ATF4 (activating transcription factor 4)
Diseases named in the same sentence as ATF4 in open-access papers (continued):
Sharing a sentence is not in itself a finding about the gene and the disease.
tumor (continued). "In response, the PERK-mediated phosphorylation of eIF2α induces LC3 puncta by activating ATF4, promoting the disposal of misfolded and protein aggregates via autophagy during tumor growth." (PMID 36497032, 2022). "ATF4-dependent tumor promotion is mediated by transcriptional targeting of the glutamate reverse transporter Xc/SLC7A11." (PMID 36430250, 2022). "Here, we show that global host ATF4 deletion significantly delays both primary and metastatic tumour growth." (PMID 35654839, 2022). "Findings show that the ferroptosis inducers erastin and RSL3 reduce ATF4-induced tumor angiogenesis." (PMID 36091118, 2022). "We and others have established a critical tumour cell intrinsic role of ATF4 that culminates in the promotion of primary growth and the establishment of metastases in xenograft, allograft and transgenic models." (PMID 35654839, 2022). "Although previous work has examined the role of ATF4 in cancer cell metabolism, prometastatic outcomes, and tumor growth in vivo, currently there is a gap in research examining ATF4 induction in response to hypoxia throughout the stages of cancer progression." (PMID 35847893, 2022). "In our study, an orthotopic xenograft mouse model was used to evaluate AR expression and its inhibitory effects on tumor growth in vivo by lentivirus-mediated delivery of ATF4." (PMID 35013318, 2022). "In this regard, more constrained deletion of ATF4 in the fibroblast/osteoblast compartment resulted in a similar tumour growth profile as in the global ATF4 KO mice." (PMID 35654839, 2022). "Several studies have reported that the tumor cell sensitivity to ONC201 is dependent on the induction of DR5 in an ATF4 and CHOP-dependent manner." (PMID 35372029, 2022). "This is the case of Transcription factor ATF4, CHOP and BiP, which counteract stress associated to tumor physiology." (PMID 35586191, 2022). "Collectively, these results suggest that host ATF4 deletion impairs the functionality of CAFs at different stages of tumour development that results in a tumour-inhibiting phenotype." (PMID 35654839, 2022). "To determine the importance of ATF4 in tumor growth in vivo, we carried out a similar xenograft study using 22Rv1 cells deleted for ATF4." (PMID 36107759, 2022). "Asparagine activates the mechanistic target of rapamycin complex 1 (mTORC1) and the activating transcription factor 4 (ATF4) in tumor cells in response to mitochondrial electron transport chain (ETC) inhibition." (PMID 36284275, 2022). "A significant inhibitory phenotype on tumour growth was also observed when host ATF4 was excised following the establishment of palpable B16F10 tumours, which provides further support for the role of ATF4 as a potential therapeutic target." (PMID 35654839, 2022). "While loss of GCN2 led to dramatically reduced tumor growth, deletion of ATF4 only delayed tumor growth relative to the wild-type parental cells." (PMID 36107759, 2022). "R=0.817, p=6.3 × 10–5) but not in vehicle (R=0.131, p=0.758) or DTX (R=0.397, p=0.158) treated tumours, suggesting that ATF4 specifically drives asparaginase-induced Asns expression." (PMID 36525288, 2022). "Specifically, ASS1 overexpression effectively inhibits tumor growth by activating PERK/eIF2α/ATF4/CHOP axis in Huh7 and SNU475 cells, indicating upregulating tumoral ASS1 expression as a promising strategy in tumors with low ASS1 expression." (PMID 35910381, 2022). "Studies have found that activating the PERK/ATF4 pathway can effectively promote tumor angiogenesis." (PMID 35327508, 2022). "ASS1, regulated by ATF4 and CEBPβ in tumor cells, is increased to enhance the synthesis of arginine from citrulline." (PMID 36231064, 2022). "Despite these reported tumor supporting properties of PKR, recent studies have shown that drug-induced PKR activation has anti-tumor effects, causing ATF4-stimulated expression of the pro-apoptotic protein NOXA, resulting in AML cell death." (PMID 36348393, 2022).
tumor (continued). "ATF4 overexpressing tumor cells release an excess of glutamate in the microenvironment, contributing to neurodegeneration and brain swelling." (PMID 35409080, 2022). "Splenomegaly is an indicator of tumor burden, and we observed generally positive correlation between ATF4 protein abundance and degree of splenomegaly." (PMID 35019856, 2022). "There were no pronounced differences in the VEGF and CXCL12 secreted levels between the tumours of different ATF4 host status." (PMID 35654839, 2022). "In total, these results indicate that host ATF4 contributes substantially to the establishment and growth of syngeneic tumours." (PMID 35654839, 2022). "Tumor volumes were lower in mice with ATF4 overexpression xenografts than in control xenograft mice." (PMID 35013318, 2022). "The GCN2-ATF4 and eIF2α-ATF4 signaling pathways also play important roles in the process of tumor cells coping with amino acid starvation and maintaining cell proliferation." (PMID 36699468, 2022). "Some levels of VEGF and CXCL12 are still present in the tumours grown in fibroblast-specific Atf4 KOs and therefore we cannot exclude some additional contribution from other sources." (PMID 35654839, 2022). "As a key factor of the AAR pathway, ATF4 is overexpressed in a variety of solid tumors, suggesting that it plays an important role in tumor progression." (PMID 35864117, 2022). "Given that both HIF1α and ATF4 are activated by distinct forms of metabolic and cellular stress, these data further point to how distinct tumor types are dependent on different types of stress signaling." (PMID 35019856, 2022). "As an important member of the ATF/CREB family, activating transcription factor 4 (ATF4) regulates tumor progression mainly through the following aspects." (PMID 34976799, 2021). "We further explored the expression of ATF4 in HCC patient samples and found that ATF4 was upregulated in tumor tissues in comparison to adjacent liver parenchyma." (PMID 34664408, 2021). "In fact, tumour cells inside a growing tumour mass, often overexpress ATF4 to alleviate the stress from rapid proliferation and limited nutrient supply." (PMID 33608585, 2021). "ATF4 is overexpressed in many forms of cancer and plays a key role in the adaption of tumour cells to the stress of rapid proliferation, nutrient and oxygen deprivation and the accumulation of misfolded proteins." (PMID 35846080, 2021). "The transcription factor JUN was reported to activate the transcription of the promoters of several key UPR effectors, such as XBP1 and ATF4, to inhibit tumour cell apoptosis." (PMID 33971902, 2021). "Thirdly, ATF4 promotes neoplastic transformation and tumor metastasis by suppressing cell senescence and anoikis, respectively." (PMID 34976799, 2021). "ATF4 expression has been reported to be upregulated in different types of human cancers and overexpression correlated with earlier tumor progression and therapy resistance." (PMID 34239013, 2021). "RPL41 can induce the degradation of the activating transcription factor 4 (ATF4) to regulate tumour cell death, cell cycle, and chemosensitivity." (PMID 34993140, 2021). "Nevertheless, our work provides consistent evidence that supports an important role of eIF2α-ATF4 axis and the integrated stress response of GB cells to conditions found in the tumor microenvironment (low glucose and hypoxia) and in response to temozolomide." (PMID 34239013, 2021). "In human immune response, ATF4 activity is induced by the exposure of immune cells in multiple stressed environments including pathogen invasion, infection, inflammation, or tumor microenvironment." (PMID 34804026, 2021). "ATF4 abundance is increased in a wide variety of human cancer cell types and tumor growth can be dependent on PERK activation and ATF4 expression." (PMID 34914716, 2021). "During the integrated stress response (ISR), ATF4 regulates tumor growth, autophagy, drug resistance, and metastasis through the PERK and GCN2 pathways." (PMID 34185683, 2021).
tumor (continued). "Our experimental study provides evidence for an important role of ATF4 for the adaptation of human GB cells to conditions of the tumor microenvironment characterized by low oxygen and nutrient availability and for the development of temozolomide resistance." (PMID 34239013, 2021). "Multivariate Cox regression analysis identified ATF4, tumor grade, and tumor differentiation as independent prognostic factors in GC." (PMID 34976799, 2021). "Recent studies have shown that tumor growth is caused by a transcriptional response through the elf2α-kinase PERK and ATF4, which activate the expression of metabolic enzymes, nutrient transporters, and mitochondrial chaperones." (PMID 34282258, 2021). "In the qRT-PCR assays of 48 PDAC tumor samples obtained in our department, a significant positive correlation was observed between ATF4 expression and ABCC1 expression (R = 0.3873, p = 0.0001)." (PMID 33782384, 2021). "In this context, EMT cells and tumor tissues show selective activation of the PERK-eIF2α-ATF4 UPR signaling axis required to promote migration and progression." (PMID 33746610, 2021). "ATF4 expression is upregulated by tumor microenvironment stress, including hypoxia and nutrient deprivation." (PMID 34437475, 2021). "This arm of the UPR is mostly related to tumor growth and survival by mediating protein synthesis through eIF2α phosphorylation and cell death in part through the ATF4/CHOP pathway." (PMID 33746610, 2021). "ATF4 depletion leads to the reduction of metastasis, cancer stemness, and tumor survival in vitro and in vivo and is involved in the TGFβ/SMAD and PI3K/mTOR pathways, playing growth factor-dependent functions." (PMID 33782384, 2021). "ERO1 deficiency reduced tumor cell migration and lung metastases by impinging on tumor angiogenesis, negatively regulating the upstream ATF4/CHOP branch of the UPR and selectively impeding oxidative folding of angiogenic factors, among which VEGF-A." (PMID 33531624, 2021). "Several other studies have also shown that the PERK/elF2α/ATF4 axis promotes therapy resistance in hypoxia tumor cells." (PMID 34282258, 2021). "ATF4 also mediates the ER stress-induced cell death of neuroectodermal tumour cells in response to fenretinide or bortezomib." (PMID 33418948, 2021). "Univariate analysis indicated that the lymph node status, tumor depth, TNM stage, tumor differentiation, ATF4 expression, and tumor grade were significantly associated with the OS of GC patients." (PMID 34976799, 2021). "Translation of the ATF4 protein is enhanced by multiple types of stresses, including oxidative stress; thus, ATF4 is thought to be involved in the resistance of tumours to chemotherapy via the regulation of xCT expression." (PMID 33210459, 2021). "Subsequently, stably downregulating ATF4 expression suppressed tumor growth and enhanced gemcitabine sensitivity in vivo." (PMID 33782384, 2021). "The downregulation of ATF4 decreases the carcinoma, whereas the upregulation of ATF4 promotes tumor progression through GCN2 activation." (PMID 34717757, 2021). "The effect was dependent on ATF4, however DNA binding analysis suggested that in tumor macrophages ATF4 was primarily impacting expression of genes involved in metabolism." (PMID 34456909, 2021). "Hypoxia-inducible factor (HIFs), sterol regulatory-element binding transcription factor (SREBFs) and activating transcription factor 4 (ATF4) are among the transcription factors that aid tumour cells in adapting to fluctuations in nutrient availability." (PMID 34262149, 2021). "Quantification of ATF4 levels in a multi‐tissue arrays of patient samples further revealed that ATF4 was highly expressed in HCC tumors as compared to non‐tumor parenchyma." (PMID 34664408, 2021). "There are only a few studies on the role of ATF4 in tumor prognosis, and the results remain controversial." (PMID 34976799, 2021).
tumor (continued). "Our results emphasize the role of glutamine depletion in the context of the ISR in human GB cells where an ATF4 upregulation possibly helps the tumor cells to adjust to altered nutrient availability." (PMID 34239013, 2021). "For example, the absence of P62 in stromal cells leads to the upregulation of ATF4 to sustain asparagine (Asn)-mediated tumor growth." (PMID 34976799, 2021). "Using pharmacological and genetic approaches we found that ATF4 directs tumor cell protective responses to mediate therapy resistance." (PMID 34239013, 2021). "PERK activation is also shown to confer hypoxia tolerance and radiotherapy resistance to different tumor cells by upregulating expression of autophagy‐related genes via ATF4 and CHOP." (PMID 32310340, 2020). "Current research shows that ATF4 plays a key role in the integrated stress response of tumor cells and can promote tumor invasion and metastasis." (PMID 32974142, 2020). "Current studies have found that ATF4 is highly expressed in a variety of tumors and plays a key role in the integrated stress response of tumor cells." (PMID 32974142, 2020). "Nutrient deprivation in tumor cells triggers endoplasmic reticulum (ER) stress with the subsequent activation of ATF4." (PMID 33396270, 2020). "These stress-proteins can regulate (inhibit) tumor generation and production alongside other transcriptional factors such as endoplasmic reticulum-ATF4, TRIB3, and CHOP, and enhance autophagy." (PMID 32839414, 2020). "Although ATF4 is known to activate pro-apoptotic factors, previous reports have established that failure to fully induce ISR by the eIF2alpha kinases PERK and GCN2 and hence to activate ATF4 reduces tumor cell growth in vitro and in vivo." (PMID 30719230, 2019). "The integrated stress response inhibitor (ISRIB) is a symmetric bisglycolamide that renders cells resistant to eIF2α phosphorylation, which attenuates the activation of ATF4, although its role in the modulation of tumor progression is yet to be elucidated." (PMID 31739582, 2019). "ATF4 presents a potential target for helping maintain the balance between Th17 and Treg cells in tumor immunity." (PMID 30978945, 2019). "Specifically, immunoblot analyses of mouse breast tissues indicated that eIF2α-P and ATF4 were decreased in the NEU mice prior to tumor formation and increased in the same mice after tumor formation compared with syngeneic mice lacking NEU." (PMID 31086176, 2019). "Further investigations are needed to elucidate how ATF4 switches its functions between cancer protection against cell death and tumor suppression in specific context." (PMID 31519193, 2019). "For example, according to Koumenis results, PERK-induced elF2α and ATF4 protects tumor cells through overcoming hypoxia." (PMID 31121863, 2019). "The anti-tumor function depends on the transcription factor ATF4, which upregulates the CDK inhibitor P21CIP1 and activates JNK1/2." (PMID 31086176, 2019). "Since pharmacological activators of the UPR, such as bortezomib, exert potent anti-tumor effects, modulators of ATF4 activation have potential in the treatment of cancer." (PMID 31461933, 2019). "We demonstrate that Sunitinib treatment activates the eIF2α/ATF4 and the autophagy pathway in GBM derived tumor cells and provide evidence of a causal link between both molecular events that constitute a ‘pro-survival’ function in a cell-type specific manner." (PMID 30719230, 2019). "GCN2 activation/overexpression and increased phospho-eIF2α were observed in human and mouse tumors compared with normal tissues and abrogation of ATF4 or GCN2 expression significantly inhibited tumor growth in vivo." (PMID 30863482, 2019). "Rationale: Activating transcription factor 4 (ATF4) is a central regulator of the cellular stress response and reduces tumor burden by controlling the expression of target genes implicated in the induction of apoptosis." (PMID 31534554, 2019).
tumor (continued). "Western blot analyses of the tumour tissues showed that ATL treatment increased the levels of ATF4, CHOP indicating activation of the ER‐stress pathway in vivo." (PMID 30609207, 2019). "ATF4 (Activating transcription factor 4), a critical regulator in unfolded protein response (UPR), is implicated in cell migration and tumor metastasis." (PMID 31064130, 2019). "The anti-tumor function of the arm depends on ATF4, which increases the expression and activity of anti-proliferative proteins like P21CIP1 and phosphorylated JNK1/2." (PMID 31086176, 2019). "We identify the transcription factor ATF4 to be a key mediator of tumor suppression by the PKR/eIF2α-P arm via the upregulation of the cyclin dependent kinase (CDK) inhibitor P21Cip1 and activation of the c-Jun-N-terminal kinase 1/2 (JNK1/2)." (PMID 31086176, 2019). "Western blotting analyses of the tumor tissues suggested that PL treatment increased the levels of ATF4, CHOP, and cleaved caspase-3, suggesting that PL-induced apoptosis in HUH-7 cells is connected to ER stress in vivo." (PMID 31680962, 2019). "Immunoblot and immunohistochemistry revealed that oxaliplatin/PL combination significantly elevated ATF4 and cleaved PARP amounts, indicating that tumor cell apoptosis was associated with ER-stress induction in vivo as well." (PMID 31395855, 2019). "In colorectal carcinoma, PERK signaling is crucial for the adaptation of cells to hypoxic stress, and activation of the PERK-eIF2α-ATF4 pathway is critical for promoting tumor dormancy, which contributes to chemoresistance in human epidermoid carcinoma cells." (PMID 30754624, 2019). "In chronic myeloid leukemia, eIF2α is constitutively phosphorylated and enhances invasive ability of tumor cells but also tumor associated stromal fibroblasts by modulating ECM remodeling through cathepsin and MMPs expression via the induction of ATF4." (PMID 31064137, 2019). "Tumor cells frequently exploit ATF4 to reduce the stress resulting from rapid proliferation and nutrient limitation inside a growing tumor mass." (PMID 31519193, 2019). "Downregulation of ATF4 in mouse NEU tumor cells by two different shRNAs reduced P21CIP1 and increased DUSP1, which was accompanied by decreased JNK1/2 phosphorylation." (PMID 31086176, 2019). "In this regard, the expression of an EMT signature is strongly correlated with ATF4 expression in datasets covering breast, colon, gastric, lung, and metastatic sites from patient tumour samples." (PMID 31071975, 2019). "We found that the ATF4/p-eIF2α pathway is activated in response to Sunitinib in primary tumor initiating progenitor cell cultures (BTICs)." (PMID 30719230, 2019). "For instance, in esophageal squamous carcinoma cells, ATF4 directly controls tumor migration in vitro and in vivo by regulating the expression of the metalloproteinases MMP2 and MMP7 that, in turn, facilitate this process via the ECM remodeling." (PMID 31064137, 2019). "The correlations among the protein levels of IRF1, PDL1, eIF2α, and ATF4 were significant in the tumor tissues, and similar patterns were found in the normal tissues except those between eIF2α and ATF4." (PMID 30305853, 2018). "Both ATF‐4 and trypsins have been shown to confer survival advantage of cancer cells and thereby to regulate tumor progression." (PMID 29193645, 2018). "The eIF2α/ATF4 pathway is responsible for the integrated stress response (ISR) of unfolded protein response (UPR) which can affect immune cell function in tumor microenvironment." (PMID 30305853, 2018). "The level of IRF7 was negatively correlated with those of PDL1, eIF2α, and ATF4 in the tumor tissue of SCC." (PMID 30305853, 2018). "The expression of IRF7 was negatively correlated with those of eIF2α and ATF4 in the tumor tissue of SCC." (PMID 30305853, 2018).